HMGB1 (high mobility group box 1)
Diseases named in the same sentence as HMGB1 in open-access papers (continued):
Sharing a sentence is not in itself a finding about the gene and the disease.
endotoxemia (continued). "We found that ATF3 protects against LPS-induced endotoxemia in mice through reducing HMGB1 expression." (PMID 24062788, 2013). "HMGB1 is a putative biomarker of inflammation in a number of diseases including endotoxemia, cystic fibrosis, and some tumors including MM." (PMID 23937860, 2013). "In light of the ability of THI-56 to attenuate LPS-induced HMGB1 release, we explored its efficacy in an animal model of lethal endotoxemia." (PMID 24098466, 2013). "Recombinant HMGB1 has been found to induce acute inflammation in animal models of lung injury and endotoxemia, and anti-HMGB1 antibody attenuated endotoxin-induced lethality even when administration of antibody was delayed until after early cytokine response." (PMID 22883976, 2012). "In fact, the administration of anti-HMGB1 antibodies or inhibitors, such as ethyl pyruvate and nicotine, significantly protected mice from LPS-induced acute tissue injury and lethal endotoxemia." (PMID 23316104, 2012). "During endotoxemia HMGB1 rises in the circulation starting at 8 hours, increasing until 16 hours, and thereafter remains at a high level until 36 h." (PMID 21726460, 2011). "Although HMGB1 is a well-known mediator of endotoxemia and a proinflammatory cytokine-like protein in vivo, purified recombinant HMGB1 only has weak in vitro proinflammatory activity, such as the induction of TNF-α production." (PMID 21660935, 2011). "Anti-HMGB1 antibodies protect against the lethal effects of LPS-induced endotoxemia in mice when administered 2 h after the onset of endotoxemia." (PMID 19799777, 2009). "HMGB1 rose in the circulation starting at 8 h, increased until 16 h, and thereafter remained at a high level until 36 h during endotoxemia." (PMID 19799777, 2009). "In light of the capacity of EGCG in attenuating LPS-induced HMGB1 release, we explored its efficacy in animal model of lethal endotoxemia." (PMID 17987129, 2007). "FPS-ZM1, a RAGE inhibitor, was used to further elucidate whether the binding of HMGB1 to RAGE determines the vascular injury function of the HMGB1/RAGE axis in endotoxemia." (PMID 39927458, 2025). "Hepatocyte Gsdmd deletion regulates HMGB1 release and inhibits vascular damage in endotoxemia." (PMID 39927458, 2025). "Furthermore, markedly increased levels of endotoxemia and serum HMGB1 levels were noted as a consequence of CYN toxicity in mice, which confirms the increased gut-leaching effect in this study." (PMID 36548732, 2022). "HMGB1 is a DAMP that is released late in endotoxemia, but early in trauma." (PMID 36726379, 2022). "Reduced HMGB1 release from hepatocytes, RAGE deficiency, and extracellular HMGB1 neutralization might prevent caspase-11-dependent pyroptosis during endotoxemia and bacterial sepsis." (PMID 36189354, 2022). "We recently show hepatocyte-released high mobility group box 1 (HMGB1) could deliver circulating LPS into the cytosol and is required for caspase-11-dependent lethality in endotoxemia and bacterial sepsis." (PMID 33854044, 2021). "Moreover, in an animal endotoxemia model, landiolol infusion suppressed the high-mobility group box 1 (HMGB-1) expression, while improving lung injury and cardiac function." (PMID 33999297, 2021). "Indeed, stimulation of the vagus nerve by physical methods (e.g., electrical or mechanical) or chemical agonists (such as nicotine and GTS-21) conferred protection against lethal endotoxemia partly by attenuating systemic HMGB1 accumulation." (PMID 34571869, 2021). "Given that (a) endotoxemia stimulates inflammasomes, (b) GSDMD blockade is protective, and (c) HMGB1 is released during endotoxemia, several groups have drawn the conclusion that HMGB1, therefore, is released in vivo by an inflammasome- and GSDMD-dependent mechanism." (PMID 32917873, 2020). "To test the hypothesis that HMGB1 release and pyroptotic cell death are spatially unrelated in endotoxemia, we used an acute intraperitoneal LPS injection model in wild-type and Gsdmd−/− mice." (PMID 32917873, 2020).
endotoxemia (continued). "The release of HMGB1 into the blood during endotoxemia has been well-documented." (PMID 32917873, 2020). "Similarly, GTS-21 can inhibit HMGB1 release from immune cells incubated with the inflammatory molecule, LPS and decrease serum HMGB1 levels in a mouse model of endotoxemia." (PMID 33126860, 2020). "HMGB1 levels reach a plateau approximately 16–32 h after the onset of endotoxemia." (PMID 31736963, 2019). "Notably, genetic deletion of NLRP3 or ASC, two essential components of the NLRP3 inflammasome, blocked LPS-, ATP- or MSU-induced HMGB1 release in cultured macrophages or during endotoxemia." (PMID 30134814, 2018). "Additionally, another endogenous neuropeptide, pituitary adenylate cyclase-activating polypeptide (PACAP), significantly reduced circulating HMGB1 levels and rescued animals in lethal endotoxemia administration." (PMID 28127491, 2017). "Furthermore, PPARγ-mediated upregulation of SIRT1 expression participates in the inhibitory action of PPARγ through deacetylation-mediated interaction of SIRT1 and HMGB1, leading to improvement of the survival of endotoxemia model mice." (PMID 28403838, 2017). "This suggests that CLEN protects from endotoxemia by targeting HMGB1." (PMID 28929026, 2017). "These mice were used to examine whether CLEN treatment can protect the mice from death by suppressing HMGB1 release into the circulation during endotoxemia." (PMID 28929026, 2017). "When seen in this light, inhibition of HMGB1 release in immune cells, which is possibly augmented in inflammatory conditions, may resolve the immune responses in the pathology of endotoxemia." (PMID 28403838, 2017). "Notably, administration of DOE ameliorated survival rates in a mouse model of endotoxemia induced by LPS, where decreased level of circulating HMGB1 was observed." (PMID 28403838, 2017). "Furthermore, administration of DOE significantly improved the survival rates in a mouse model of endotoxemia, with a concomitant reduction in the level of circulating HMGB1." (PMID 28403838, 2017). "We therefore examined whether the acetylation status of HMGB1 is related to the lethality and survival rate of endotoxemia model mice." (PMID 26522327, 2015). "A decade-long search has culminated in HMGB1 as a late toxic cytokine of endotoxemia." (PMID 24348831, 2014). "Previous studies indicate endotoxemia results in its up-regulation of HMGB1." (PMID 25309129, 2014). "We further hypothesized that GL could protect against porcine endotoxemia through modulation of the systemic inflammatory response by reducing the serum level and gene expression of HMGB1 and other pro-inflammatory cytokines." (PMID 23497622, 2013). "Notably, the administration of rosiglitazone to mice improved survival rates in an LPS-induced animal model of endotoxemia, where reduced levels of circulating HMGB1 were demonstrated." (PMID 23316104, 2012). "Therefore, the inhibition of hepatocyte GSDMD had a greater protective effect on endotoxemia than did hepatocyte-specific Hmgb1 knockout, and other factors that are released may depend on hepatocyte GSDMD activation and have a lethal effect on endotoxemia." (PMID 39927458, 2025). "Notably, HMGB1-induced pyroptosis has been observed in vivo during endotoxemia." (PMID 41280917, 2025). "However, in vivo studies are needed to elucidate whether hepatocytic GSDMD regulates endothelial GSDMD-mediated vascular injury through the release of HMGB1 in endotoxemia." (PMID 39927458, 2025). "Loss of hepatocyte HMGB1, inhibition of hepatocyte HMGB1 release, neutralization of extracellular HMGB1 or RAGE deficiency could prevent caspase-11-dependent pyroptosis and death in endotoxemia and bacterial sepsis." (PMID 35720285, 2022). "Furthermore, neutralizing extracellular HMGB1 or inhibition of HMGB1-LPS binding could prevent caspase-11-dependent pyroptosis and death in endotoxemia." (PMID 33552058, 2020).
endotoxemia (continued). "Notably, blockade of HMGB1 signals by these reagents confers cellular protection from delayed endotoxin lethality in a mouse model of endotoxemia, even when applied after the acute phase of cytokine responses has peaked, indicating that HMGB1 is a novel target for inflammatory diseases." (PMID 28403838, 2017). "Thus, based on the changes in hippocampus 5-HT level, we wondered whether classic HMGB-1/TLR4 related inflammation pathway participates in the pathological process of endotoxemia induced acute neuro-inflammation." (PMID 28059131, 2017). "In addition, p38-dependent inhibition of HMGB1 release was also demonstrated in cellular or animal models of severe acute pancreatitis and endotoxemia upon administration of the natural products glycyrrhizin, Dachengqi decoction, and the tetrahydroisoquinoline alkaloid THI-28." (PMID 28403838, 2017). "Moreover, GL could reduce the serum level and gene expression of HMGB1 and other proinflammatory cytokines and protect vital organs against porcine endotoxemia." (PMID 25541713, 2014). "However, it is unclear whether ATF3 plays a role in the HMGB1 regulation of LPS-induced endotoxemia." (PMID 24062788, 2013). "High extracellular levels of HMGB1 correlate with IL-6/TNF-α production and are strong indicators of severe systemic inflammation and lethal endotoxemia." (PMID 41472211, 2025). "In endotoxemia, we demonstrated that hepatocyte GSDMD was responsible for regulating the release of HMGB1." (PMID 39927458, 2025). "To verify the necessity of the interaction of HMGB1 with RAGE in vascular injury, we also induced endotoxemia by intratracheally instilling LPS, which allowed the LPS to be evenly distributed in the lungs of the mice." (PMID 39927458, 2025). "HMGB1 interacts with RAGE and subsequently participates in endothelial GSDMD-mediated vascular injury in endotoxemia." (PMID 39927458, 2025). "In 1999, we discovered that high mobility group box 1 (HMGB1) was released by endotoxin-stimulated macrophages and monocytes, and functioned as a late mediator of lethal endotoxemia." (PMID 39763679, 2024). "It was also demonstrated that the process of HMGB1 endocytosis requires the RAGE and dynamin-dependent signaling, which in turn influences macrophage pyroptosis during endotoxemia." (PMID 34867376, 2021). "Administration of FeTPPS significantly attenuates HMGB1- and caspase-11–mediated GSDMD cleavage, organ damage, and lethality in endotoxemia and bacterial sepsis." (PMID 33854044, 2021). "Given the ability of several herbal components to inhibit LPS-triggered cellular responses for inflammation, we investigated the effect of a 60% ethanol extract of D. odorifera on HMGB1 release in LPS-treated RAW264.7 cells and a mouse model of endotoxemia." (PMID 28403838, 2017). "In line with this notion, the deacetylation-mediated interaction of HMGB1 and SIRT1 in mice was sufficiently potent to robustly protect against endotoxemia in response to LPS challenge by inhibiting the secretion of HMGB1 and cytokines such as TNF-α and IL-6." (PMID 26522327, 2015). "BALB/c mice infected with Ad-Flag-HMGB1, Ad-Flag-HMGB1K282930R, and/or Ad-Myc-SIRT1 via the tail vein were challenged with LPS to induce lethal endotoxemia." (PMID 26522327, 2015). "Here, we report that HMGB1 release is modulated by SIRT1 in macrophages and an animal model of endotoxemia." (PMID 26522327, 2015). "We further demonstrated that ATF3 gene knockout in mice subjected to LPS-induced endotoxemia correlates with an increase in the mortality rate and the elevated expression of IL-6, TNF-α, NO, MCP-1, and HMGB1 in the lung tissues or serum." (PMID 24062788, 2013). "It decreases the levels of high-mobility group box 1 (HMGB1) protein and lipopolysaccharide in the plasma in experimental endotoxemia." (PMID 21569368, 2011).
endotoxemia (continued). "Therefore, the results of these in vivo experiments verified that hepatocyte GSDMD mediated HMGB1 release and subsequently regulated endothelial GSDMD-mediated vascular injury in endotoxemia." (PMID 39927458, 2025). "For instance, a major component of Gancao, glycyrrhizin (GZA), could directly bind HMGB1 to disrupt its engagement with RAGE receptor, thereby conferring protection against lethal endotoxemia by inhibiting HMGB1-mediated inflammation." (PMID 34571869, 2021). "In addition, HMGB1 is released via SAA-mediated TLR4 receptor activation and SAA-neutralizing antibodies are protective against endotoxemia in septic patients." (PMID 30833653, 2019). "Thus, administration of anti-HMGB1 antibodies inhibited LPS-induced TNF levels in vitro and during endotoxemia." (PMID 30975096, 2019). "Unlike other pro-inflammatory cytokines, HMGB1 is a "late-appearing" inflammatory mediator, because its release during endotoxemia is delayed in comparison with the rapid increase of early pro-inflammatory cytokines such as IL-1β, IL-6 and TNF-α." (PMID 19799777, 2009). "Previous studies have shown that HMGB1 enables extracellular LPS to induce non-canonical inflammasome activation in macrophages, which is critical for the activation of coagulation cascades during endotoxemia." (PMID 40992080, 2025). "However, it warrants further studies to demonstrate whether the production and release of TNF-α, IL-1βand IL-6 is altered in HMGB1/TLR4 signaling pathway and whether this is the main pathological mechanism in endotoxemia induced acute neuro-inflammation." (PMID 28059131, 2017). "SIRT1 inhibited LPS- or TNF-α-induced HMGB1 release from macrophages by directly interacting with HMGB1 in an acetylation-dependent manner; therefore, we next analyzed whether SIRT1 affected the circulating HMGB1 level during endotoxemia, a standard model of systemic inflammation." (PMID 26522327, 2015).
rheumatoid arthritis (108 papers, 2008 to 2025). A chronic, systemic autoimmune disorder characterized by inflammation in the synovial membranes and articular surfaces. "M2 macrophages in the rheumatoid arthritis (RA) synovial microenvironment are particularly susceptible to ferroptosis, where the HMGB1/ Toll-like Receptor 4 (TLR4)/STAT3 axis plays a pivotal role in exacerbating synovial inflammation." (PMID 41326356, 2025). "Elevated levels of HMGB1 are associated with many inflammatory-mediated diseases and organ injuries such as lung injury, myocardial infarction, and rheumatoid arthritis." (PMID 37520569, 2023). "The beneficial effects of EP in animal models of T1D, rheumatoid arthritis, systemic lupus erythematosus, autoimmune orchitis, and inflammatory bowel disease were also associated with HMGB1 inhibition in the tissues targeted by the pathogenesis." (PMID 34944410, 2021). "Moreover, the amplification of the PGE2 biosynthesis pathway by HMGB1/IL-1β is suggested as an important pathogenic mechanism perpetuating inflammatory and destructive activities in rheumatoid arthritis." (PMID 31560698, 2019). "The amplification of the PGE2 biosynthesis pathway by HMGB1 might constitute an important pathogenic mechanism perpetuating inflammatory and destructive activities in rheumatoid arthritis." (PMID 23488692, 2013). "Circulating HMGB1, the prototype member, has a crucial role in sterile inflammation caused by tissue injury or mitochondria damage, while its levels are increased in many human inflammatory diseases such as rheumatoid arthritis and their associated experimental models." (PMID 30804932, 2019). "During pathological conditions such as rheumatoid arthritis, HMGB1 is kept in its reduced isoform and can complex with CXCL12 enhancing cell migration and exacerbating the immune responses." (PMID 41937914, 2025). "HMGB1 is highly expressed in various inflammatory and autoimmune diseases, such as including sepsis, rheumatoid arthritis (RA), and systemic lupus erythematosus (SLE), acting as a DAMP to trigger inflammatory responses and exacerbatee disease progression." (PMID 40236711, 2025). "Excessive levels of HMGB1 can be seen in patients with rheumatoid arthritis, whereas antibodies against HMGB1 can be seen in patients with Sjogren’s syndrome." (PMID 37808964, 2023). "Similar to this study, there was an improvement of inflammation by the significant reduction of HMGB1 and MMPs expression in rheumatoid arthritis after glycyrrhizin treatment." (PMID 34953035, 2022). "Increased HMGB1 expression has been demonstrated in inflammatory joint diseases such as rheumatoid arthritis, osteoarthritis and synovitis." (PMID 34953035, 2022). "In patients with rheumatoid arthritis, the production of HMGB1 and the number of cells secreting HMGB1 at specific inflammation areas are elevated." (PMID 33776579, 2021). "Conversely, a recent study showed that HMGB1 is maintained in a reduced state, owing to the activity of the thioredoxin antioxidant system, in monocytes from patients with active rheumatoid arthritis." (PMID 32670275, 2020). "HMGB1 is a lethal inflammatory mediator; studies have shown that HMGB1 participates in disseminated intravascular coagulation, severe acute pancreatitis, burns, hemorrhagic shock, rheumatoid arthritis, systemic lupus erythematosus, and other diseases." (PMID 33050676, 2020). "It has been shown that extracellular HMGB1 induces angiogenesis and promotes rheumatoid arthritis via NF-κB/HIF-1α activation, and cilostazol inhibits NF-κB-mediated transcription leading to the inhibition of synovial angiogenesis." (PMID 32328193, 2020). "Reported values of HMGB1 levels in synovial fluid from patients with rheumatoid arthritis ranged from 50 ng/ml to 10.4 mg/ml." (PMID 31929852, 2019). "HMGB1, a key mediator of inflammation, plays an important role in initiating OA and rheumatoid arthritis." (PMID 30542285, 2018).